IL24 (interleukin 24)
Diseases named in the same sentence as IL24 in open-access papers (continued):
Sharing a sentence is not in itself a finding about the gene and the disease.
tumor (continued). "The antitumor activity was proven to occur by IL-24 protein affecting the IL-24 receptor-positive tumor endothelial cells and inhibiting tumor angiogenesis." (PMID 24377906, 2013). "In vivo studies confirmed the in vitro findings and demonstrated IL-24 protein suppressed growth of lung tumor xenograft by inhibiting tumor angiogenesis." (PMID 24377906, 2013). "Biological assays showed 10% to 30% of the tumor mass was transduced following Ad-IL24 treatment that resulted in 70% of the tumor cells showing signs of apoptosis." (PMID 24377906, 2013). "It is possible that IL-24 inhibits the Akt/mTOR signaling pathway in endothelial cells akin to that observed in the tumor cells." (PMID 24377906, 2013). "Although IL-24 was reported to be a tumor suppressor, the biological functions of IL-19 and IL-24 are different." (PMID 24130695, 2013). "IL-24 suppresses multiple signaling pathways in a broad-spectrum of human cancer cells leading to tumor cell death, inhibition of tumor angiogenesis and metastasis." (PMID 24377906, 2013). "The consensus from the large number of studies reported till date is that IL-24 functions as a tumor suppressor and IL-24-mediated cytotoxicity is selective towards tumor cells with minimal to no toxicity to normal cells." (PMID 24377906, 2013). "Results from preclinical and clinical studies have established IL-24, a member of the IL-10 super-family, functions as a tumor suppressor/cytokine gene." (PMID 24377906, 2013). "Since STAT-3 is known to signal for cell survival and proliferation, the importance of IL-24 mediated STAT-3 activation was tested using STAT-3 inhibitors in IL-24 receptor-positive tumor cells." (PMID 24377906, 2013). "In preclinical studies, MDA-7/IL-24 therapy has been shown to slow tumor progression both in vitro and in vivo." (PMID 22808125, 2012). "After combination of IL-24 and TRAIL, excellent anti-tumor gene TRAIL-L-IL-24 (L is linker) and excellent anti-tumor effect will be obtained to complete eradication of xenograft tumor (submitted)." (PMID 23675261, 2012). "Interleukin-24 (IL-24) is an important immune mediator, as well as a broad-spectrum tumor suppressor." (PMID 22640485, 2012). "Delivery of IL-24 by liposome or adenovirus can specifically inhibit growth of tumor cells and induce tumor-specific apoptosis." (PMID 22640485, 2012). "The enhanced anti-tumor toxicity of SM7L involves enhanced modulation of the ERK and MAPK signaling pathways, key mediators of MDA-7/IL-24 tumor toxicity." (PMID 22808125, 2012). "MDA-7/IL-24 that selectively kills cancer cells and decreases survival in adjacent tumor cells as a profound ‘bystander effect’ represents an appealing molecule for cancer gene therapy." (PMID 22629368, 2012). "The primary goal of this study was to enhance the therapeutic potential of MDA-7/IL-24 by designing a new molecule that exploits the anti-tumor domain of wild-type MDA-7/IL-24." (PMID 22808125, 2012). "The in vitro anti-tumor activity of oncolyticadenovirus SG600-IL-24 was significantly greater than that of replication defectiveadenovirus IL-24." (PMID 22569271, 2012). "IL-24 was hailed as a novel and interesting development inexperimental tumor therapy in the early 21st century." (PMID 22569271, 2012). "The most potent (or one of the strongest) anti-tumour gene is IL-24 (interleukin-24) compared with more than twenty anti-tumour genes studied in our lab." (PMID 23675261, 2012). "A recombinant type five adenovirus containing IL-24 gene (designated CNHK600-IL24) was constructed, whose replication is activated only in tumor cells." (PMID 22640485, 2012). "IL-24 acts as tumor suppressor whose ectopic production has been reported to inhibit invasion and migration of human cancer cells." (PMID 22723936, 2012). "Such a tight relationship between Bcl-2 denitrosylation and ubiquitination sheds new light on IL-24-induced Bcl-2 degradation and specific tumor apoptosis." (PMID 22629368, 2012).
tumor (continued). "To augment efficacy of IL-24, we searched for acomplementary anti-tumor protein to deliver in combination therapy." (PMID 22569271, 2012). "In recent years, the synergistic anti-tumor effects of IL-24, including apoptosis-inducing and immune-stimulating effects have gained increasing attention." (PMID 22640485, 2012). "Among the other genes we transferred to the Cocca-6A cells, we tested the pro-apoptotic and tumor suppressor properties of Mda-7/IL-24." (PMID 22666387, 2012). "These i.p. tumor-bearing mice were divided into groups and treated as follows: treated with IL-24-containing nanocarrier, treated with adenovirus (Ad)-IL-24, treated with Ad-luciferase (Luc), or treated with phosphate buffered saline (PBS)." (PMID 21490751, 2011). "The failure of IFNαA to inhibit tumor growth in our mouse models reinforces a need to consider alternate biotherapeutic strategies, such as TNFα or IL-24 that are known to have anti-angiogenic properties." (PMID 21401924, 2011). "Although the majority of reports focus on IL-24 as a tumor suppressor gene a few studies have investigated immune modulating properties of IL-24 and its potential role in inflammatory diseases." (PMID 20072629, 2010). "The findings of the present study have important implications for the understanding of IL-24 not only as an immune modulating cytokine but also as a tumor suppressor gene." (PMID 20072629, 2010). "Onconase treatment consistently resulted in up-regulation of IL-24, previously shown to have tumor suppressive activity, as well as ATF3 and IL-6." (PMID 20137089, 2010). "Secreted IL-24 has been reported to be anti-angiogenic and to sensitize tumor cells to radiation therapy and chemotherapy." (PMID 20072629, 2010). "The tumor suppressor effects of IL-24 include inhibition of angiogenesis, sensitization to chemotherapy, and p38 mitogen-activated protein kinase (MAPK)-mediated apoptosis." (PMID 20072629, 2010). "As discussed in the present work these findings have important implications for our understanding of IL-24 as a tumor suppressor protein as well as an immune modulating cytokine." (PMID 20072629, 2010). "In general, research on IL-24 can be divided into two categories: IL-24 as a classical cytokine with immune modulating properties or IL-24 as a protein with tumor suppressor effects." (PMID 20072629, 2010). "Previous studies from our laboratory and others showed mda-7/IL-24 inhibit human tumor cell proliferation by inducing cell cycle arrest at G2/M phase." (PMID 17274815, 2007). "Interleukin-24 (IL-24) is recognized for its anti-tumor activity, although its role in immune regulation remains unclear." (PMID 41898874, 2026). "At present, IL-24 is the only cytokine of the IL-20 subfamily with tumor suppressor activity." (PMID 40806452, 2025). "Hence, this pathway map would accelerate clinical applications of IL-24 as a therapeutic target for various disorders, to its potential as a prominent therapeutic agent in cancer, and to reshape the tumor microenvironment." (PMID 40661937, 2025). "However, the effects of VGg-IL-24 on various immune cells have not been clarified, and most of them are limited to the direction in which IL-24 can induce tumor cell apoptosis." (PMID 40469178, 2025). "Interleukin 24 (IL-24) is a tumor-suppressing protein currently in clinical trials." (PMID 40072085, 2025). "In ARMS, IL-24 overexpression leads to decreased tumor cell survival, growth, and motility." (PMID 40508013, 2025). "We and others have previously shown that IL-24 exerts its tumor suppression effect in cancer cells by endoplasmic reticulum (ER) stress activation, reactive oxygen species (ROS) accumulation, p38 MAPK activation, mitochondrial dysfunction, and ceramide production while not affecting normal cells." (PMID 40072085, 2025).
tumor (continued). "IL24 exerts its anti-tumor effects through multiple mechanisms, including the induction of pro-apoptotic genes such as caspases, suppression of angiogenesis, and modulation of the tumor immune microenvironment." (PMID 40076725, 2025). "Additionally, combined treatments involving radiation, chemotherapy, and small molecule inhibitors have been examined to enhance the anti‐tumor activity of IL‐24." (PMID 40338095, 2025). "IL-24 primarily functions as a tumor-suppressive cytokine via multiple mechanisms, including inhibition of invasion, migration, angiogenesis, and metastasis, induction of apoptosis, elimination of cancer stem cells, and sensitization of cancer cells to therapies." (PMID 40607413, 2025). "Notably, other than the effects on wound healing observed on a receptor-dependent manner, IL-24 has been revealed in promoting tumor cell-specific apoptosis, maintaining Th17 homeostasis and ER homeostasis through a receptor-independent way." (PMID 38752989, 2025). "Previous studies have primarily focused on the killing effect of IL-24 on tumor cells." (PMID 40469178, 2025). "Conversely, TXNIP could suppress tumor growth by upregulating IL-24 and downregulating p-STAT3 signaling." (PMID 40175348, 2025). "Notably, IL-24 exhibits selective toxicity toward tumor cells with minimal effects on normal tissues, underscoring its potential for clinical application." (PMID 40866941, 2025). "In the context of NKG2D-expressing exosomes, the enhanced expression of NKG2D driven by IL24 could improve the ability of NK-Exos to recognize and bind to tumor cells expressing NKG2D ligands (NKG2DLs)." (PMID 40076725, 2025). "IL-24 activated anti-tumor immunity and eliminated primary and distant tumors." (PMID 40469178, 2025). "As a tumor-suppressive cytokine, IL-24 induces apoptosis in cancer cells, while sparing normal cells, and inhibiting angiogenesis within the tumor, thereby restricting tumor growth and spread and enhancing the immune system’s ability to detect and destroy tumor cells." (PMID 40607413, 2025). "Clinical studies correlate decreased IL-24 expression with tumor progression and a poor prognosis." (PMID 39664443, 2024). "Additionally, CSF synergizes with other cytokines, such as IL-24, to amplify the body’s tumor immune response." (PMID 38259287, 2023). "TRAIL was shown to be upregulated in tumor cells after Ad/IL-24 infection and studies of the apoptotic cascade regulators indicate that Ad/IL-24 could further enhance the activation of apoptosis through the TNF family of death receptors." (PMID 37280571, 2023). "The contribution of autophagy in Mda-7/IL-24 tumor inhibitory roles is controversial." (PMID 37280571, 2023). "Macrophage stimulating 1 (Mst1) enhances IL24-based anti-tumor via inactivating ERK-Mfn2 pathway." (PMID 37580749, 2023). "The anti-tumor effect is further improved when IL-24 combine with DDP." (PMID 37182136, 2023). "The inhibition effect of IL-24 on Ishikawa cell proliferation and tumor growth was verified both in vivo and in vitro, which may be mediated by Bcl-2 downregulation." (PMID 36531027, 2022). "Moreover, concerning the mechanism through which IL-24 assists tumor clearance, a rise in caspase-9 and TRAIL levels was detected, which indicates the high involvement of the apoptotic pathway." (PMID 35752792, 2022). "Thus, the anti-tumour efficiency of poxvirus vector—VV Tian Tan strain Guang 9 expressing GM-CSF in different murine tumour models was evaluated alone and in combination with IL-24." (PMID 36140243, 2022). "melanoma differentiation associated gene-7 or Interleukin-24 (mda-7, IL-24) displays expansive anti-tumor activity without harming corresponding normal cells/tissues." (PMID 35402258, 2022). "In this study, it was observed that IL-10 blockade could increase the capacity of our adjuvant E7&IL-24 vaccine in eradicating tumor cells, which was further proved by an increase in the level of IFN-γ and caspase-9." (PMID 35752792, 2022).
tumor (continued). "The recruitment of IL-24 at the tumor site was validated and quantified by IHC." (PMID 35752792, 2022). "Furthermore, the obtained tumor tissue from the IL-24 group contained a higher amount (P < 0.05) of IL-24 cytokine when compared with the E7 group." (PMID 35752792, 2022). "In turn, IL-24 displays anti-tumor activity and can inhibit angiogenesis." (PMID 35371972, 2022). "We found that B.breve-IL-24 induced activation of caspase-3 and Bim in tumor tissues, the results could be found in our previous study." (PMID 35814447, 2022). "Both luteolin and IL-24 have been shown to inhibit tumor growth through the activation of the JNK signaling pathway, but whether the combination therapy can enhance the activation of the JNK signaling pathway still needs further studies." (PMID 36146619, 2022). "As a potential antitumor gene, IL-24 inhibits tumor growth, metastasis, invasion, and angiogenesis." (PMID 35292065, 2022). "IL-24 is also an important immune mediator in addition to a tumor-suppressing agent." (PMID 35292065, 2022). "IL-24 is involved in immune response and anti-tumor activity." (PMID 35884907, 2022). "To address this deficiency, we investigated whether combining the E7 DNA vaccine with MDA-7/IL-24 as an adjuvant would elicit efficient antitumor responses in tumor-bearing mouse models." (PMID 35752792, 2022). "To explain these two opposing phenomena, we hypothesized that MDA-7/IL-24-induced IFN-γ upregulated PD-L1 expression in B16 tumor cells resulting in the escape of a subset of B16 cells from T cell-mediated killing." (PMID 35402258, 2022). "Targeting the elevation of IL-24 could probably inhibit lymphangiogenesis and limit the tumor’s aggressiveness." (PMID 35885529, 2022). "The research completed previously has shown that ectopic expression of mda-7/IL-24 using transfection of tumor cells with plasmid cDNA or adenovirus-mediated delivery, or exposure to a purified protein results in the suppression of tumor cell growth." (PMID 35008495, 2021). "Ad-mediated delivery of MDA-7/IL-24/CTV is very efficient in inhibiting tumor growth when delivered intratumorally, however, systemic administration of these therapeutic viruses may be necessary to achieve maximum benefit and for better disease control." (PMID 35008495, 2021). "The results documented that MDA-7/IL-24 expression could delay tumor onset in MMTV-MDA-7/MMTV-Erbb2 compound transgenic mice, and could also suppress tumor growth and exhibit “bystander” antitumor effects in MMTV-PyMT mice." (PMID 35008495, 2021). "Interleukin 24 (IL-24) has been shown to be a tumor suppressor." (PMID 34944995, 2021). "In this context, AhR and IL24 might be used as composite targets for screening anti-tumor migration compounds in there." (PMID 34955744, 2021). "Furthermore, IL24 belongs to the IL10 gene family that possess antitumor properties including inhibition of tumor angiogenesis and induction of tumor cell apoptosis." (PMID 34771568, 2021). "Similarly, treatment of tumor xenografts with MDA-7/IL-24 reduces expression of angiogenesis markers." (PMID 35008495, 2021). "Administration of MDA-7/IL-24-producing T cells was associated with elevation of mRNA levels of human MDA-7/IL-24, and mouse TNF-α, and IFN-γ in prostate tissues, as a result of T-cell trafficking to the tumor sites and homing to lymphoid organs." (PMID 35008495, 2021). "And these finding also show that VV‐IL‐24 combined with luteolin which had a stronger efficacy in vivo may contributed to the increased IL‐24 gene expression and the inhibition of tumor cells proliferation and angiogenesis." (PMID 33274495, 2021). "Since both luteolin and IL‐24 have been shown to inhibit tumor growth through the JNK signaling pathway, whether the combination therapy can enhance the activation of the JNK signaling pathway still needs further confirmation." (PMID 33274495, 2021).
tumor (continued). "In addition, the expression of two tumor-suppressor genes—IL-24 and GADD45A—was upregulated in E2-treated PDXs, as well as in organoids that were isolated from E2-treated tumors, depending on treatment time." (PMID 34944995, 2021). "The anticancer effect of IL‐24 also includes the bystander effect killing nearby tumor cells." (PMID 33274495, 2021). "Similarly, IL24 can also induce tumor cell death through various mechanisms including endoplasmic stress induced apoptosis, autophagy, anti-angiogenesis and immune activation." (PMID 33790740, 2021). "MDA-7/IL-24 functions as a potent tumor suppressor exerting a diverse array of functions including the inhibition of tumor growth, invasion, angiogenesis, and metastasis, and induction of potent “bystander” antitumor activity and synergy with conventional cancer therapeutics." (PMID 35008495, 2021). "The anti-tumor activity of IL24 is mainly attributed to endogenous gene expression." (PMID 34955744, 2021). "Our previous data have demonstrated that the exogenous IL-24 gene harbored in the viral genome of ZD55-IL-24 was able to be highly expressed in many kinds of human tumor cells and played an important role in immunocompromised mouse–human tumor xenograft models." (PMID 33257647, 2020). "mda-7/IL-24 in particular seems especially promising given its potential to treat not only a wide array of solid tumors, but also to treat metastasis, inhibit tumor angiogenesis and stimulate anti-tumor immune response." (PMID 33126767, 2020). "Notably, it has been proven that decreasing the WBC and lymphocytes resulted in the reduction in levels of cytokines such as interleukin 24 (molecular weight 23 kDa), which plays an important role in tumor immunosuppression." (PMID 33396882, 2020). "Importantly, high concentration of IL-24 remarkably reduced both peripheral and tumor-infiltrating Treg frequency (Tukey tests, all P < 0.0001)." (PMID 31921658, 2019). "IL-24 has multiple mechanisms of anti-tumor effects, including inducing tumor cell apoptosis, promoting “bystander” effects, and enhancing immunogenicity of tumor cells by upregulating costimulatory molecules that favor activation of T cells." (PMID 31338417, 2019). "However, it had been found that some tumor cells over-expressed anti-apoptotic protein Bcl-2 and antagonized the IL-24 function." (PMID 31781493, 2019). "However, high concentration of IL-24 notably down-regulated FoxP3 mRNA relative level in both peripheral and tumor-infiltrating CD4+ T cells (Tukey tests, P < 0.0001)." (PMID 31921658, 2019). "Antitumor effects induced by LX/IL-24-infected tumor cells were first examined in vitro." (PMID 31338417, 2019). "Their study showed that a combination of two anti-tumor genes (IL-24 with TRAIL) may be a promising strategy for gene-viro therapy, which exhibits a synergistic anti-tumor effect." (PMID 31781493, 2019). "Mice immunized with B16-LX/IL-24 significantly inhibited tumor growth." (PMID 31338417, 2019). "IL-24 is a potential anti-tumor agent and affects a broad array of cancers, which selectively inhibits tumor cell growth, invasion, metastasis, and angiogensis, induces cancer-selective apoptosis, stimulates anti-cancer immune response, sensitizes cancer call to therapies." (PMID 31921658, 2019). "The highest amount of IL-24 productions were at 48 hr in tumor cells after LX/IL-24 infection." (PMID 31338417, 2019). "Another selective PI3K inhibitor, 3-MA acts on Vps34 and PI3Kγ and significantly enhances IL-24-induced apoptosis in oral squamous cellcarcinomas (OSCC), which demonstrates the combination of autophagy inhibitors and IL-24 is a promising approach for tumor immunotherapy." (PMID 30678689, 2019). "Moreover, low concentration of IL-24 promoted FoxP3 mRNA expression in tumor-infiltrating CD4+ T cells (Tukey test, P = 0.012)." (PMID 31921658, 2019). "Therapeutic effects of LX/IL-24-infected tumor vaccine were furtherly determined in C57BL/6 mice." (PMID 31338417, 2019).